Y_RNA (Y RNA )
Gene: Miscellaneous RNA gene on chromosome 10 (68,735,720 to 68,735,823, reverse strand). Ensembl gene ENSG00000195401.
Homologues: Orthologues: macaque Y_RNA (88% identical). Paralogues in human: Y_RNA (77% identical), Y_RNA (76% identical), Y_RNA (75% identical), Y_RNA (74% identical), RNY1 (73% identical), Y_RNA (73% identical), Y_RNA (72% identical), Y_RNA (71% identical), RNY1P5 (70% identical), Y_RNA (70% identical), RNY1P9 (69% identical), Y_RNA (69% identical), and 89 more.